CTNNB1 (catenin beta 1)
Diseases named in the same sentence as CTNNB1 in open-access papers (continued):
Sharing a sentence is not in itself a finding about the gene and the disease.
tumor (continued). "Four genes (BDNF, PTGS2, GSK3B, and CTNNB1) were significantly upregulated and one gene (HPGD) was significantly downregulated in primary tumor tissues compared with adjacent normal tissues throughout all the five in silico datasets." (PMID 35054980, 2022). "Downstream of the TGF-β pathway, SMAD3 and CTNNB1 form a complex with other molecules in the nucleus and induce EMT, proliferation, and angiogenesis in desmoid tumor cells via the SMAD2/3 pathway." (PMID 36497457, 2022). "In contrast, FOXH1 increased the mRNA levels of CTNNB1 and Wnt target genes in breast cancer cell lines, and depletion of β-catenin reversed the positive effects of FOXH1 on tumor cell proliferation and invasion." (PMID 34298659, 2021). "Upregulation of tumor signatures, such as GPC3, DUSP9, and CTNNB1 can be observed in tumor cells and PDX." (PMID 34497364, 2021). "Promoter hypermethylation of CTNNB1, a known oncogene, seems inconsistent with a role in tumorigenesis; however, RASSF1A is a tumor suppressor for which promoter hypermethylation has been detected in many cancers." (PMID 34680217, 2021). "CTNNB1 expression positively correlated with both m6A writers and IGF2BP2 in 38 paired CCA tumor and adjacent normal tissues, which was further validated by data sets in TCGA database." (PMID 34347395, 2021). "In this review, we examine the evidence for genomic, phenotypic, and tumor microenvironment ITH in HCC, with a focus on two of the top molecular drivers of HCC: β-catenin (CTNNB1) and Telomerase reverse transcriptase (TERT)." (PMID 34771685, 2021). "Though very few DEGs were apparent in GTx‐024‐treated tumor‐free controls (n = 27), GSEA focused on TF pathways revealed abundant coordinated signaling with regulation of β‐catenin (CTNNB1) target genes providing the most significant overlap (FDR < 1e‐5)." (PMID 31930715, 2020). "In agreement with previous findings, we found that ATP6AP2 expression is higher in tumor tissues than that in normal tissues, moreover, level of ATP6AP2 expression in GBM is positively correlated with those of CTNNB1, CCND1 and AGT." (PMID 32143717, 2020). "Moreover, we cannot exclude that tumour heterogeneity lowered the mutated allele frequencies of the reference mutations, particularly in PIK3CA, and thus could have resulted in a false interpretation of CTNNB1 mutational homozygosity." (PMID 33115416, 2020). "DNER regulates its downstream target RBPJ and SKP1, and also interacts with the important factors of Wnt signaling pathways, CTNNB1 and CDH2, regulating tumor proliferation, differentiation, invasion, migration and angiogenesis of PanNENs tumorigenesis." (PMID 33329729, 2020). "Analysis of the CTNNB1-pathways and WT1-pathways suggested that they are differentially regulated across these tumor regions." (PMID 32843649, 2020). "CTNNB1 and CDH2 were localized at the cell membrane, and we found strong cell membrane positivity of CTNNB1 and CDH2 in tumor tissue compared with paratumor tissue, with significant differences (P < 0.05)." (PMID 33329729, 2020).
tumor (continued). "Intravenous delivery of CTNNA1 siRNA with CA nanoparticles significantly reduced tumor volume in the initial phase of the study, while siRNAs targeting CTNNB1, TLN1, VCL, PXN, and ACTN1 genes significantly decreased the tumor burden at all time points." (PMID 31269666, 2019). "Further more, we confirmed decreased expression of CTNNB1 downstream transcription factor TCF4 and target gene Cyclin D1 in METTL3 knockout HB cell Huh6 and tumor-bearing tissues of mice." (PMID 31870368, 2019). "However, there is no saying whether the mutation of CTNNB1 is an early phenomenon in tumorigenesis contributing to the appearance and growth of the tumor or a later event caused by the accelerated cell division characteristic of neoplasms." (PMID 31266530, 2019). "Tumor formation in mice proved that HCG11 was negatively correlated with miR-1276 and had positively correlation with CTNNB1." (PMID 31889902, 2019). "The absence of CTNNB1 mutations supports the hypothesis of Rocha and coworkers that loss of E-cadherin expression rather than β-catenin (CTNNB1) gene mutations induces the process of tumour dedifferentiation." (PMID 29133385, 2018). "Wnt signalling probably facilitates the phosphorylation of CTNNB1 and APC by GSK3B and is likely to function as a tumor suppressor." (PMID 30447692, 2018). "In particular, we found that TMEM30A regulates several migration-related genes including SUB1, SLC2A1, CTNNB1, ACTB, and CLTC during tumor migration, which further demonstrates the effectiveness of our proposed method." (PMID 28640862, 2017). "Our findings here highlight how in some contexts, excessive activation of specific CTNNB1 target genes can reduce CRC cell and tumor growth." (PMID 27333864, 2016). "As WNT7A activates tumor growth and progression in OvCa via the WNT7A/CTNNB1 signaling pathway, downregulation of miR-15b allows aberrant WNT7A expression is further support the impact of WNT7A and its mechanisms in OvCa." (PMID 27195958, 2016). "The intranuclear role of CTNNB1 as transcription cofactor was connected to IGF2 and part of complex karyotype tumours in their study." (PMID 27429002, 2016). "In the tumor‐adjacent mucosa, this was confirmed only for RACGAP1 and CTNNB1 (r = 0.401, P = 0.003)." (PMID 26778597, 2016). "Answering these questions is the key to understanding why CTNNB1/TCF activity can both promote and suppress tumor growth and stem cell-like properties, depending on the cellular and transcriptional context." (PMID 27333864, 2016). "Nuclear CTNNB1 acts as a transcriptional coactivator with TCF/LEF transcription factors, promoting expression of a broad set of target genes, some of which promote tumor growth." (PMID 27333864, 2016). "In this study, IHC staining with the four antibodies, and tumor “activity,” did not correlate with β-catenin mutation, and there was no clear difference in CTNNB1 mutation between Sets A and B of the earlier gene expression study, although a larger study might identify a correlation." (PMID 24402778, 2014).
tumor (continued). "The expression data revealed an increased (≥3-fold) expression of transcriptional regulators in HCC-R tumor tissues (MYC (3.72), CTNNB1 (3.19), and MDM2 (4.27))." (PMID 24377043, 2013). "On the contrary, proliferation-promoted genes such as CTNNB1, CREB1, CREB5, and TCF7L2 were up-regulated 3.65-, 2.63-, 2.87-, and 5.75-fold respectively in tumor tissues." (PMID 23285163, 2012). "Analysing these residual tumour cells we identified a gene expression pattern encompassing GSK3B, CTNNB1 and NOTCH2, which strongly predicts prognosis of the patients." (PMID 22970250, 2012). "Multivariate Cox regression analysis indicated that tumor recurrence, low-level of miR-214 and CDH1, and high-level of EZH2 and CTNNB1 were prognostic factors for early HCC recurrence and poor survival." (PMID 22962603, 2012). "Genes of this pathway up-regulated in CC tumor cells were JUN, MYC, FZD2, RAC1, GSK3B and CTNNB1, and a few others." (PMID 17822553, 2007). "Similarly, WNT pathway alterations—particularly in CTNNB1 and APC—were enriched in H/L patients with PC and GC, reinforcing their potential role in driving tumor biology in this population." (PMID 40869017, 2025). "LEF-1 staining significantly correlated with CTNNB1 staining (R2= 0.1283, p= 0.0046), although with discrepancies at the individual sample level as these were not consecutive slides of the tumour." (PMID 40130164, 2025). "Interestingly, compared to normal tissues, SPP1+ TAMs-CAFs regulated tumor cells through the regulation of genes related to HCC tumorigenesis, including CCND1, MYC, CTNNB1, and BAX." (PMID 40230843, 2025). "ENKUR may be a tumor suppressor via recruiting FBXW7 to directly ubiquitinate and degrade CTNNB1 in EC." (PMID 39990660, 2025). "Decrease in hCTNNB1, indicative of tumor burden driven by mutant-CTNNB1, was enhanced in the LNP-CTNNB1 + α-PD1 compared to LNP-CTNNB1 + IgG treated mice (p = 0.0395) suggesting an augmented response to LNP-CTNNB1 with α-PD1." (PMID 40442146, 2025). "While CTNNB1 mutations are critical for ACP initiation, they are not essential for the proliferation of tumor epithelium." (PMID 40299526, 2025). "Although molecular profiling (e.g., CTNNB1 or TERT promoter mutations) was not available, the tumour's strong beta-catenin and Glypican-3 expression supported a diagnosis of HCC." (PMID 41583252, 2025). "Wnt/β-catenin signaling activates CTNNB1 (β-catenin) through WNT1, promoting the expression of collagen (such as COL1A1 and COL28A1), thereby increasing the adhesion and matrix invasion ability of tumor cells." (PMID 40989695, 2025). "Applying similar tumor microenvironment oriented analytical strategies to THBS2, CTNNB1, COL4A1, and E2F3 may offer deeper insight into their roles in shaping immune suppression, stromal remodeling, and treatment response in STAD." (PMID 41291892, 2025). "Other somatic mutations associated with VTE independent of tumor type include KRAS, STK11, MET, KEAP1, CTNNB1, and CDKN2B." (PMID 39851266, 2025). "Prior to testing efficacy of siRNA-mediated CTNNB1 knockdown in HCC, we assessed whether there were any effects of the LNP itself on the tumor immune microenvironment (TIME)." (PMID 40442146, 2025). "FMRP interacts with both GSK3β and CTNNB1, MSI1 represses APC and enhances Wnt signaling in epithelial progenitors, while MEX3A stabilizes LGR5 and represses DKK1, thereby promoting stemness and tumor progression." (PMID 41516083, 2025). "Before testing efficacy of siRNA-mediated CTNNB1 knockdown, we assessed whether there were any adjuvant effects of the LNP itself on the tumor immune microenvironment (TIME)." (PMID 39711542, 2024).
tumor (continued). "Elevating Ctnnb1 in high-miR-17-92 cells does not raise β-catenin protein levels, suggesting that other factors regulated by miR-17-92 contribute to tumor inhibition, potentially negatively affecting β-catenin production." (PMID 38534736, 2024). "Some studies indicated that all carried activated CTNNB1 mutations in tumor patients have disease progression, and non-WNT pathways changes of tumor patients were significantly more likely to respond or gain clinical benefit from immunotherapy." (PMID 38665910, 2024). "On the other hand, CTNNB1 knockdown inhibits the Wnt/β-catenin signaling pathway and downregulates the expression of downstream genes, including axin 2, lymphoid enhancer-binding factor 1 (LEF1), and cyclin D1, thereby inhibiting tumor proliferation." (PMID 37033970, 2023). "To investigate the mechanism of cooperation of these two frequent alterations, we first compared CTNNB1 and 11p15.5 spectra of alterations in the tumors occurring in patients with or without 11p15.5 mosaic in their corresponding non-tumor liver." (PMID 37932266, 2023). "The KD appeared to reduce liver weight/body weight ratio and significantly suppressed tumor multiplicity and total tumor volume, reproducing the phenotype observed in the Scd2f/f;CC mice and validating the role of LTB4R2 in CTNNB1 and YAP1 activation and liver tumorigenesis in vivo." (PMID 37156770, 2023). "As a result of a systematic search for single and combined drug treatments, we found that overexpressing the activity of “CTNNB1” (forcing its value to 1) would not prevent tumor growth but would greatly limit the invasive capacity." (PMID 37289551, 2023). "In contrast, in tumours characterized by sequencing as exon 3 exclusion tumours, an average of 12% of the total number of Ctnnb1 transcripts detected by BaseScope did not include exon 3, corroborating on tissue sections the results from the splicing analysis." (PMID 37907668, 2023). "Again, none of the three CTNNB1 (c.65_100del, c.94G > C, and c.100G > A) and AKT1 (c.49G > A) mutations in the initial LBC sample were found in the tumour tissue by deep sequencing." (PMID 39516270, 2023). "Furthermore, we explored the TMN plot to compare VEGFA, CTNNB1, MMP7, and CD44 oncogenes in tumor and metastatic CRC samples from RNA sequencing data (RNAseq)." (PMID 36672201, 2023). "Additionally, in catenin beta 1 (CTNNB1) mutant HCC, the increased phosphorylation of ALDOA at Ser36 can also promote glycolysis and subsequently facilitate tumor growth." (PMID 35912218, 2022). "Non-phospho CTNNB1 (i.e., active CTNNB1) was detected in tumor tissues of TGFBR1-CA ovaries, whereas its expression was restricted to early stage follicles in the control ovaries." (PMID 35565312, 2022).
tumor (continued). "The hub genes, including PIK3R1, CTNNB1, JUN, EGFR, and APP, might play an important role in tumor development." (PMID 35733630, 2022). "Since recent studies have shown the efficacy and tolerance of sitagliptin as cancer therapeutic, it would be interesting to further investigate its activities as a target for DPP4/CTNNB1/MET signaling pathways in THCA, both in vitro and in vitro in tumor-bearing mice." (PMID 35205190, 2022). "We chose to examine the interplay between genetic factors (TERTp and CTNNB1) in the tumor and immune factors (cytotoxic CD8+ cells) in the tumor microenvironment and their prognostic value in terms of time to recurrence (TTR), DFS and OS among resected HCC patients." (PMID 35962322, 2022). "Guided by the RNA-seq finding, we revealed ovarian WNT signaling activation in TGFBR1-CA mice by demonstrating the localization of non-phosphorylated active CTNNB1 to the tumor foci." (PMID 35565312, 2022). "While we and others did not detect liver tumors up to 6 mo after hepatic Ctnnb1 exon 3 deletion, we observed spontaneous tumor formation 11.5 mo after β-catenin activation in mouse liver in this study, similar to a very recent report." (PMID 36122209, 2022). "CTNNB1 mutated HCC does not show any inflammatory cell infiltration, therefore, it is considered to be a ‘cold’ tumor." (PMID 34201284, 2021). "The risk of relapse in tumours with CTNNB1 exon 3 mutation was independent of FIGO stage, tumour grade, mismatch repair protein expression, or the presence of lymphovascular space invasion." (PMID 34420090, 2021). "Therefore, the tumor-suppressive effect of the EMX1/EMX2 genes measured in terms of the proliferative rate and clone formation is lost when mutant CTNNB1 is overexpressed." (PMID 34364391, 2021). "We speculated that HOXB9 might block the Wnt signaling pathway and inhibit tumor growth through MYC and CTNNB1." (PMID 34306077, 2021). "Subsequently, compared with mice inoculated with a mixture of SMMC-7721 cells and TAMs that were transfected with a vector, we found that tumour growth rate and tumour load were remarkably reduced in mice inoculated with a mixture of SMMC-7721 cells and TAMs that had either silenced Wnt2b or CTNNB1." (PMID 33407720, 2021). "For the castration-induced regression nadir group (i.e., those with the weakest or most unsuccessful castration-induced tumor regression), GSE1, CYP3A5, CTNNB1, CYP3A4, POU5F1, ABCB1, alkaline phosphatase liver/bone/kidney isozyme (ALPL), PROM1/CD133, ABCG2, and SOX2 were concomitantly upregulated." (PMID 34439112, 2021). "Another novel finding is our observation of the negative association between CTNNB1 mutation and the presence of MELF pattern in these tumours." (PMID 34420090, 2021). "pegRNA Ctnnb1 S45 deletion-treated animals showed extensive tumor formation, whereas pegRNA SERPINA1-treated animals did not induce any tumor formation." (PMID 33837189, 2021). "Instead, targeted SOX2 + stem cells give rise to β-catenin-accumulating cell clusters, while the tumours originate from a different cell lineage as they do not express the lineage reporter, nor do they contain a Ctnnb1 exon 3 deletion." (PMID 34019103, 2021).